LINC00642 (long independently transcribed non-coding RNA 642)
Gene: Long non-coding RNA gene on chromosome 14 (90,449,602 to 90,508,469, forward strand). Ensembl gene ENSG00000233208.
Diseases named in the same sentence as LINC00642 in open-access papers:
LINC00642 is named in the same sentence as 1 disease in open-access papers, as found by Europe PMC text mining. Sharing a sentence is not in itself a finding about the gene and the disease.
LINC00642 shares sentences with these, for which no sentence is quoted: Alzheimer disease (1 paper).